CSTA (cystatin A)
Description:
This is an intracellular thiol proteinase inhibitor. Has an important role in desmosome-mediated cell-cell adhesion in the lower levels of the epidermis.
Synonyms: STF1; STFA; AREI; PSS4
Tractability: Small molecule: a structure with a bound ligand is known. Antibody: its Gene Ontology location is reachable by antibodies, with high confidence. PROTAC: ubiquitination databases record sites on it; its protein half-life has been measured.
Gene: Protein-coding gene on chromosome 3 (122,325,248 to 122,341,969, forward strand). Ensembl gene ENSG00000121552.
Subcellular location: Cytoplasm
Subcellular location (Human Protein Atlas): Cytosol; Nucleoplasm
Pathways (Reactome):
Developmental Biology: Formation of the cornified envelope
Gene Ontology:
Molecular function: cysteine-type endopeptidase inhibitor activity; protease binding; protein binding; endopeptidase inhibitor activity
Biological process: cell-cell adhesion; keratinocyte differentiation; negative regulation of proteolysis; peptide cross-linking
Cellular component: cornified envelope; cytoplasm; extracellular region; peptidase inhibitor complex; cytosol
Genetic constraint (gnomAD): Loss-of-function variants: 4 observed, 7.49 expected, observed/expected ratio (o/e) 0.53, 90% interval 0.26 to 1.22. That is too few expected variants to judge how well the gene tolerates losing a copy. Missense variants: 102 observed, 96.37 expected, observed/expected ratio (o/e) 1.06, 90% interval 0.9 to 1.25. Synonymous variants: 32 observed, 36.17 expected, observed/expected ratio (o/e) 0.88, 90% interval 0.67 to 1.19.
Homologues: Orthologues: chimpanzee CSTA (100% identical), macaque CSTA (93% identical), dog CSTA (79% identical), rabbit CSTA (71% identical), rat Stfa2 (64% identical), rat Stfa2l3 (64% identical), mouse Csta1 (63% identical), rat Stfa2l1 (62% identical), rat Stfa2l2 (62% identical), rat Csta (60% identical), mouse Cstdc4 (59% identical), mouse Stfa3 (59% identical), and 11 more. Paralogues in human: CSTB (53% identical).
Diseases named in the same sentence as CSTA in open-access papers:
CSTA is named in the same sentence as 79 diseases in open-access papers, as found by Europe PMC text mining. Sharing a sentence is not in itself a finding about the gene and the disease. The quoted sentences say what the papers report.
breast carcinoma (11 papers, 2006 to 2023). "CSTA deregulation has been associated with different cancer types, and specifically breast cancer." (PMID 31429720, 2019). "Down-regulation of CSTA expression after the treatment of E2 in ERα-positive breast cancer cells were reported." (PMID 35976950, 2022). "CSTA was found to be down-regulated in esophageal squamous cell cancer, prostate cancer, skin cancer, and breast cancer." (PMID 29581829, 2018). "In some forms of highly malignant and metastasizing breast cancer, there is a correlation between increased CSTA expression and poor prognosis." (PMID 25785582, 2015). "Interestingly, both increased cysteine protease inhibition and cystatin A expression were associated with better survival in NSCLC, and enforced expression of CSTA reduced metastasis in breast cancer." (PMID 29581829, 2018). "Interestingly, the gene cystatin A (CSTA), a cystein proteinase inhibitor, which is among the 49 core up-regulated genes has been proposed as a prognostic marker for breast cancer." (PMID 20078854, 2010). "In malignant tissues, cystatin A has been found in many tumors including breast cancer." (PMID 17092354, 2006). "Cystatin A is a human cysteine proteinase inhibitor first identified from the cytosol of human polymorphonuclear granulocytes and has been shown to play roles in various cancers (i.e., colorectal cancer, breast cancer, non–small-cell lung cancer) and diseases (i.e., psoriasis, glaucoma)." (PMID 37301378, 2023).
lung cancer (8 papers, 2013 to 2023). A malignant neoplasm involving the lung. "Taken together, CSTA is down-regulated in lung cancer cell lines, and CSTA has a potential diagnostic value in sub-classification of non-small cell lung cancer (NSCLC)." (PMID 29581829, 2018). "Our finding of lower levels of cystatin A in the urine of women with endometrial cancer is consistent with previous work where cystatin A has been reported to act as a tumour suppressor in oesophageal and lung cancers." (PMID 36807337, 2023). "Its main function is to protect cells from the hydrolysis of cytoskeletal and cytoplasmic proteins by cathepsins B, H, and L. CSTA has been documented to serve a suppressive role in esophageal squamous cell carcinoma and in lung cancer cell lines." (PMID 36193204, 2022). "Cystatin A expression (which inhibits cathepsins B, H and L) was down-regulated in lung cancer cell lines and over-expressed cystatin A inhibited cathepsin B-mediated colony formation, migration and invasion." (PMID 31212661, 2019). "Here we found that CSTA was down-regulated in all lung cancer cell lines compared to normal lung epithelial cells." (PMID 29581829, 2018). "CSTA was restored in most lung cancer cell lines after treatment with demethylation agent 5-aza-2-deoxycytidine and deacetylation agent Trichostatin." (PMID 29581829, 2018). "Previously, by using suppression subtractive hybridization (SSH), we observed that CSTA mRNA was down-regulated in lung cancer cell lines (D51, H226 and H2170) compared to normal human bronchial epithelial cells (HBEC)." (PMID 29581829, 2018). "Therefore, the study was aimed to analyze the epigenetic regulation and function of CSTA with special focus on EMT in lung cancer cells." (PMID 29581829, 2018). "However, there is limited knowledge concerning the role of CSTA on cell phenotype transition during lung cancer development." (PMID 29581829, 2018). "Taken together, the data indicate that TGF-β induced EMT could be prevented by CSTA-mediated inactivation of the MAPK pathway in lung cancer cells." (PMID 29581829, 2018). "Based on these findings, we speculate that CSTA prevents TGF-β1-induced EMT by modulating the MAPK pathway in lung cancer cells." (PMID 29581829, 2018). "Collectively, CSTA overexpression prevents the process of EMT in lung cancer cells." (PMID 29581829, 2018). "After treatment with TSA, we found that CSTA expression was significantly up-regulated in six lung cancer cell lines (H23, H2030, H226, H1650, COLO677 and H1975) and slightly increased in three cell lines (H2170, H1299 and H322), whereas no CSTA restoration was detected in H157 and A549." (PMID 29581829, 2018). "Firstly, we found that down-regulation of CSTA was a frequent molecular event in lung cancer cells." (PMID 29581829, 2018). "Taken together, our data suggest that CSTA acts as a tumor suppressor and inhibits tumor cell growth through inhibiting EMT in lung cancer cells." (PMID 29581829, 2018). "In lung cancer and head and neck cancer, positive staining of CSTA was significantly related to squamous carcinoma (SCC) compared to adenocarcinoma (ADC), additionally, in head and neck cancer, reduced CSTA expression was correlated with tumor recurrence." (PMID 29581829, 2018). "However, so far the function of CSTA has not yet been elucidated in lung cancer." (PMID 29581829, 2018). "To further confirm the role that DNA methylation plays in CSTA gene expression, we knocked down DNMT1 (left) in 4 lung cancer cell lines, and found that down-regulation of DNMT1 led to a significantly increased CSTA expression in H23 and COLO677, but not H226." (PMID 29581829, 2018).
exfoliative ichthyosis (6 papers, 2014 to 2025). Exfoliative ichthyosis is an inherited, non-syndromic, congenital ichthyosis characterized by the infancy-onset of palmoplantar peeling of the skin (aggravated by exposure to water and by occlusion) associated with dry, scaly skin over most of the body. "Studies have shown that mutations in the CSTA gene encoding Cystatin-A are associated with acral peeling skin syndrome and exfoliative ichthyosis." (PMID 32602849, 2020). "Loss-of-function mutation in CSTA, a gene encoding cystatin A, can induce autosomal recessive exfoliative ichthyosis with reduced thickness of CE and abnormalities in the lamellar body." (PMID 32054030, 2020). "Mutations in CSTA are associated with skin fragility phenotype including exfoliative ichthyosis and acral peeling skin syndrome." (PMID 29581829, 2018). "More recently, we discovered that mutations in the CSTA gene are the underlying genetic cause of the skin fragility condition known as exfoliative ichthyosis with impaired cell-cell adhesion in the lower layers of the epidermis." (PMID 25785582, 2015). "In the autosomal recessive disorder exfoliative ichthyosis, loss-of-function mutations in CSTA results in coarse peeling of the skin on the palms and soles and detachment occurring in the lower epidermis with abnormal desmosomes." (PMID 25785582, 2015). "Our results complement the recent findings showing that loss-of-function mutations in the CSTA gene is the underlying cause of the skin condition exfoliative ichthyosis." (PMID 25785582, 2015). "Sanger sequencing of CSTA in a different family with exfoliative ichthyosis revealed a homozygous nonsense mutation which also segregated with disease." (PMID 25093584, 2014). "Sequence capture and NGS of this region was then performed and revealed a splice site mutation in CSTA, which was found to segregate with exfoliative ichthyosis in the Bedouin family." (PMID 25093584, 2014). "The discovery of cystatin A (CSTA) gene mutations in association with exfoliative ichthyosis is an example of the successful implementation of combining SNP microarray analysis with targeted NGS to determine the genetic cause of disease." (PMID 25093584, 2014). "In addition, loss-of-function mutations in CSTA were identified as cause of exfoliative ichthyosis, highlighting the expression of CSTA in keratinocytes and a role in desmosome-mediated cell-cell adhesion." (PMID 29581829, 2018).
nasopharyngeal carcinoma (5 papers, 2011 to 2025). A carcinoma arising from the nasopharyngeal epithelium. "This study aims to investigate the expression of macrophage inflammatory protein-3 alpha (MIP-3α) and cystatin A in nasopharyngeal carcinoma (NPC) and their association with clinical characteristics and prognosis." (PMID 26634210, 2015). "This study was aimed to investigate the roles of serum macrophage inflammatory protein-3α (MIP-3α) and cystatin A in nasopharyngeal carcinoma (NPC) prognosis." (PMID 25396333, 2014). "Serum level of CSTA has been proposed as a tool predicting nodal stage and poor prognosis in nasopharyngeal carcinoma." (PMID 22673103, 2012). "Similarly, nasopharyngeal carcinoma (NPC) patients with elevated levels of CSTA in their blood have poor prognostic outcomes." (PMID 40007784, 2025).
psoriasis (4 papers, 2012 to 2025). An autoimmune condition characterized by red, well-delineated plaques with silvery scales that are usually on the extensor surfaces and scalp. "The review of SNPs of CSTA, ERAP1 and ZAP70 genes, which were tested for correlation with the risk of psoriasis." (PMID 27658291, 2016).
Alzheimer disease (3 papers, 2013 to 2024). A progressive, neurodegenerative disease characterized by loss of function and death of nerve cells in several areas of the brain leading to loss of cognitive function such as memory and language. "Alzheimer disease patients showed also significantly higher levels of α-defensins 1–4, Tβ4, cystatin A, and the dimeric and glutathionylated proteoforms of cystatin B." (PMID 34121996, 2021).
esophageal cancer (3 papers, 2014 to 2024). A primary or metastatic malignant neoplasm involving the esophagus. "In the other clusters, the genes SCML4, HNRNPF, IFRD1, CSTA, ABL1, etc., have a causal relationship with esophageal cancer." (PMID 38434988, 2024). "Similarly, genes like SCML4, HNRNPF, IFRD1, CSTA, ABL1 in other immune cell clusters also exhibit a causal relationship with esophageal cancer." (PMID 38434988, 2024). "So far few publications indicate the tumor suppressive function of CSTA in esophageal cancer." (PMID 29581829, 2018). "C-Jun increased the promoter activities of cystatin A, involucrin, and SPRR3 in a dose-dependent manner, suggesting that c-Jun activates the promoters of these differentiation-associated genes in vivo in esophageal cancer cell line." (PMID 24796531, 2014).
squamous cell carcinoma (3 papers, 2013 to 2018). A carcinoma arising from squamous epithelial cells. "Loss of CSTA leads to decreased cell-cell adhesion by disrupting desmosomal structures in epidermoid carcinoma cells." (PMID 29581829, 2018). "CSTA is deregulated in several skin cancers, including squamous cell carcinomas (SCC) and loss of function mutations lead to recessive skin fragility disorders." (PMID 25785582, 2015). "In primary lung tumors, squamous cell carcinoma (SCC) significantly expressed more CSTA compared to adenocarcinoma (p<0.00001), and higher expression of CSTA was significantly associated with lower tumor grade (p<0.01)." (PMID 29581829, 2018). "Genes associated with squamous cell cancer, KRT5, cystatin A (CSTA) tumor protein p63 (TP63) and SOX2, were expressed at higher levels in ASC, but also expressed to some extent in the AC." (PMID 24324581, 2013).
bladder cancer (2 papers, 2020 to 2025). "Other candidates include BRINP1 (silenced in some bladder cancers), CD7 (associated with leukaemia), CSTA (encodes a stefin that functions as a cysteine protease inhibitor, suggested as a prognostic tool for cancer), and SUPT20H (a known tumour rejection antigen)." (PMID 32872585, 2020). "In bladder cancer tissues, CST1, CST2, CST6, CSTA, and CSTB were significantly upregulated, while CST3 and CST7 were downregulated compared to benign tissues." (PMID 40747123, 2025). "CST6, CSTA, and CSTB were upregulated, while CST3 and CST7 were downregulated in bladder cancer tissues." (PMID 40747123, 2025). "In this study, our results from benign bladder tissues and cancer cell lines showed that CST3, CST6, CSTA, and CSTB were the predominant isoforms out of the 14 family members expressed by bladder cancer cells." (PMID 40747123, 2025).
Breast tumors (2 papers, 2019 to 2025). "Loss of CSTA expression in breast tumors disrupts the balance of cysteine proteases, leading to enhanced extracellular matrix remodeling, tumor invasion, and metastasis." (PMID 41325308, 2025). "Breast tumors with positive CSTA expression are associated with poor patient outcome." (PMID 31429720, 2019).
diabetes (2 papers, 2019 to 2025). "CSTA's role in platelet‐dependent thrombus formation, particularly its elevated expression in diabetes, is echoed in our findings, linking it to COPD and thrombotic events in COPD patients." (PMID 40045538, 2025). "We provide evidence that CSTA, the StfA human ortholog, was present in both human MKs and platelets, upregulated during obesity/diabetes and was released during platelet activation." (PMID 31270351, 2019). "We also evidenced an upregulation (7- to 9.7-fold) of genes encoding stefin A (StfA), the human ortholog of Cystatin A (CSTA), inhibitor of cathepsin B, H and L. StfA/CSTA was present in megakaryocytes and platelets and its expression increased during obesity and diabetes in rats and humans." (PMID 31270351, 2019).
epithelial dysplasia (2 papers, 2014 to 2015). "The expression of cystatin A, involucrin and SPRR3 was remarkably decreased during the malignant transformation from normal epithelium to low-grade intraepithelial neoplasia (LGIN) or high-grade intraepithelial neoplasia (HGIN)." (PMID 24796531, 2014).
esophageal squamous cell carcinoma (2 papers, 2022 to 2025). Esophageal squamous cell carcinoma (ESCC) is a type of esophageal carcinoma (EC) that can affect any part of the esophagus, but is usually located in the upper or middle third. "In the case of esophageal squamous cell carcinoma (ESCC), for instance, early tumors display a much lower level of CSTA expression, but more advanced tumor regions display relatively higher levels, which may be a reaction to increased protease activity." (PMID 40007784, 2025).
head and neck cancer (2 papers, 2018 to 2020). A primary or metastatic malignant neoplasm affecting the head and neck. "Among them, CSTA downexpression was significantly associated with poor overall survival in head and neck cancers." (PMID 32528874, 2020). "Thus, CSTA may play important roles in the progression of head and neck cancer and serve as a potential biomarker for future diagnosis and treatment." (PMID 32528874, 2020). "Finally, the protein level of CSTA, which was validated by the Human Protein Atlas (HPA) database, was down-regulated consistently with mRNA levels in head and neck cancer samples." (PMID 32528874, 2020).
invasive carcinoma (2 papers, 2015 to 2017). A carcinoma that is not confined to the epithelium, and has spread to the surrounding stroma. "A role for cathepsin B is further supported by studies showing that suppression of cystatin A, an endogenous inhibitor of cathepsin B, increases progression of DCIS to invasive carcinoma." (PMID 28506312, 2017).
liver cancer (2 papers, 2014 to 2023). An epithelial or non-epithelial malignant neoplasm that arises from the liver. "As a result, we aimed to confirm whether inhibiting SMPD2 or CSTA enhances the sensitivity of liver cancer cells to lapatinib." (PMID 37006285, 2023).
lung squamous cell carcinoma (2 papers, 2018 to 2022). "CSTA was identified as a squamous cell lung carcinoma-associated gene." (PMID 35584089, 2022).
melanoma (2 papers, 2021 to 2023). A malignant, usually aggressive tumor composed of atypical, neoplastic melanocytes. "We found LOR, EVPL, SPRR1A, FLG, DSP, and CSTA had been reported in previous studies on melanoma." (PMID 35003328, 2021).
metastatic tumor (2 papers, 2009 to 2022). "CSTA (cystatin A, or stefin A), a cysteine proteinases inhibitor, is implicated in preventing local and metastatic tumor spread of cancers." (PMID 20015385, 2009). "Conversely, chloroquine treatment impaired autolysosomal flux and exacerbated malignance, showing jeopardization of p62/ Sqxtm1 turnover, leading to Yap accumulation, which is also consistent with overexpression of cystatin A (CSTA) in situ with pancreatic cancer cells and metastatic tumor." (PMID 35326559, 2022).
pancreatic cancer (2 papers, 2022 to 2025). "In the present study, we evaluated whether CSTA has an anticancer effect in mouse models of pancreatic cancer." (PMID 39792573, 2025).
prostate carcinoma (2 papers, 2022 to 2025). A carcinoma that arises from epithelial cells of the prostate gland. "On the other hand, in other malignancies, such as prostate cancer, elevated CSTA levels are connected to less severe disease, which highlights the dual nature of the role that CSTA plays in cancer." (PMID 40007784, 2025).
acne (1 paper, 2022). An inflammatory process of the sebaceous glands which is characterized by comedones, nodules, papules and/or pustules on the skin. "At 3q21.1, there is further evidence supporting the importance of cell-cell adhesion processes in the skin in acne susceptibility through the identification of CSTA as the putative causal gene at this locus." (PMID 35132056, 2022).
atopic dermatitis (1 paper, 2015). "CSTA was originally identified as a precursor protein of the cornified cell envelope and reduced expression of CSTA contributes to a defective epidermal barrier in the skin condition known as atopic dermatitis." (PMID 25785582, 2015).
cervical cancer (1 paper, 2023). A primary or metastatic malignant neoplasm involving the cervix. "Expression appeared to be increased in patient-derived tissue diagnosed with cervical cancer in the Human Tissue Atlas, but the level of cystatin A appeared to be dependent on the antibody used." (PMID 37301378, 2023).
colon cancer (1 paper, 2014). "Incubation with pioglitazone or telmisartan only significantly downregulated relative PPARγ mRNA expression in all three colon cancer cell lines, while upregulating CSTA in an evidently dose-dependent manner." (PMID 25360175, 2014).